BRAF (B-Raf proto-oncogene, serine/threonine kinase)
Diseases named in the same sentence as BRAF in open-access papers (continued):
Sharing a sentence is not in itself a finding about the gene and the disease.
colorectal cancer (continued). "Here, blood samples were obtained from 105 patients that contained different cancer driver gene mutations, such as NSCLC patients with an EGFR gene mutation and colorectal cancer patients with a BRAF mutation." (PMID 32180799, 2020). "BRAF V600E mutation exists in approximately 5–7% of late-stage colorectal cancer as previously reported and was demonstrated to have a significant increase based on patient age in several studies." (PMID 33194656, 2020). "BRAF mutations are common in colorectal cancer and confers significant prognosis to advanced diseases." (PMID 33247170, 2020). "BRAF mutation is present in 15% of colorectal cancers, and the role of mutations in WNT signaling regulators in this context is unclear." (PMID 32384699, 2020). "Raf murine sarcoma viral oncogene homolog B (BRAF)-mutated colorectal cancers (CRCs) are found in a subgroup of CRCs with distinctive clinicopathological features." (PMID 33152998, 2020). "Next, we investigated the impact of MCM7 knockdown in other colorectal cancer cell lines harboring KRAS or BRAF mutations." (PMID 32612138, 2020). "Here, we have investigated the role of somatic mutation in shaping the WNT signaling landscape of colorectal cancers bearing the BRAF mutation." (PMID 32384699, 2020). "BRAF-mutated colorectal cancer exhibits distinct clinicopathological features from wild-type BRAF cancer independent of the microsatellite instability status." (PMID 32481270, 2020). "Colorectal cancer with a mutation in an oncogene BRAF has paid much attention, as it comprises a population with dismal prognosis since two decades ago." (PMID 33152998, 2020). "BRAF mutant colorectal cancers with truncating APC mutation tended to arise earlier in life, and presented at a significantly later stage." (PMID 32384699, 2020). "Here we have conducted a large-scale genomic analysis of the somatic mutations that underlie WNT signaling activation in BRAF mutant colorectal cancer." (PMID 32384699, 2020). "Little is known about the clinical significance of BRAF Non-V600E mutations' role in lung cancer, however, it's recently been associated with colorectal cancer." (PMID 32850378, 2020). "The combination of seeMet 12 and the BRAF inhibitor sorafenib was then assessed as a potential combination strategy, as cMet is often highly overexpressed in colorectal cancers, whereas BRAF mutations are present in approximately 10% of metastatic cases." (PMID 33014851, 2020). "Molecular diagnostic testing of KRAS and BRAF mutations has become critical in the management of colorectal cancer (CRC) patients." (PMID 32923312, 2020). "Cutaneous metastasis of colorectal cancer with BRAF V600E mutation is a rare but important phenomenon that should not be ignored." (PMID 32481270, 2020). "Hundred percent of the mutations found in breast cancer were located in ERBB2 and similarly, BRAF accounts for all mutations in colorectal cancer and MAP2K1 in pancreatic cancers." (PMID 32757330, 2020). "Co-targeting the Wnt pathway using FAK inhibitors was proposed as a new approach to overcome resistance to BRAF inhibitors in BRAF-mutated colorectal cancer patients." (PMID 33266025, 2020). "It has also been found that the mutation of BRAF protein in patients with colorectal cancer has an adverse prognosis, causing mortality rates to increase by 70% as compared with normal BRAF backgrounds." (PMID 32033142, 2020). "The BRAF V600E mutation is detected in 35–43% of dMMR colorectal cancers, but is rare in Lynch-associated colorectal cancers, even though they are dMMR." (PMID 31286289, 2020). "Dose-response curve of the (D) MDST8 colorectal cancer cell lines with BRAF mutation treated with dabrafenib." (PMID 33274713, 2020). "Future prospective studies are needed to better understand the predictive value of BRAF V600 mutations in MMR-D colorectal cancer patients who are treated with immune checkpoint inhibitors." (PMID 32670606, 2020).
colorectal cancer (continued). "BRAFV600E is the most prevalent mutation accounting for more than 90% in BRAF mutant colorectal cancers." (PMID 33738242, 2020). "High and low CpG island methylator phenotypes in colorectal cancer are associated with BRAF mutations or KRAS mutations, respectively." (PMID 31937368, 2020). "Previous studies have shown that BRAF mutation is a poor prognostic factor in colorectal cancer patients." (PMID 32481270, 2020). "In contrast, when used alone, these drugs produce only minimal benefits in BRAF-mutant colorectal cancer because they cause reactivation of RAS (via a feedback mechanism) or activation of signaling through the PI3K/AKT pathway." (PMID 32066410, 2020). "Activation of RAS/MAPK pathways through mutations of RAS family members and BRAF are classical driver mutations of colorectal cancer." (PMID 33520689, 2020). "For instance, BRAF mutations in colorectal cancer were detected as a sensitivity biomarker for dabrafenib by the Bayesian test, but less significant by the ANOVA test." (PMID 33274713, 2020). "Here we thoroughly overviewed the basic, translational and clinical studies on colorectal cancer with BRAF mutation from a physician’s viewpoint." (PMID 33152998, 2020). "Data from the literature reported KRAS and BRAF mutations’ roles as prognostic and predictive biomarkers among patients undergoing colorectal cancer liver metastases hepatic resection." (PMID 32858990, 2020). "The genotype analyses revealed right-side colorectal carcinoma with BRAF mutation, and liver metastasis lesion appeared later." (PMID 32785802, 2020). "KRAS or BRAF alterations with concomitant PI3KCA mutation were found in colorectal carcinomas in 7–9% and 1–12%, respectively." (PMID 33081092, 2020). "Mutations in the BRAF gene have been described in several types of tumors and it is widely known that the HT-29 cell line has a mutated BRAF (V600E) while the other colorectal carcinoma cell lines tested (SW-480 and SW-620) harbor wild type BRAF." (PMID 33198289, 2020). "We have previously demonstrated that MGL ligand expression is associated with BRAF mutations in colorectal cancer." (PMID 30761272, 2019). "Overall, we confirmed the clinical utility of BNA-clamp PCR for detecting KRAS, NRAS and BRAF mutations in colorectal cancers." (PMID 31711486, 2019). "BRAF mutations occur in approximately 10% of colorectal cancers and are associated with resistance to anti-EGFR therapy." (PMID 31711486, 2019). "SERPINE2, a member of the serine protease inhibitor nexin superfamily, contributes to the invasion in solid tumours and more specifically in colorectal cancers bearing KRAS or BRAF mutations." (PMID 30651148, 2019). "Non-V600E BRAF mutated colorectal cancer (CRC) is a rare disease entity with specific clinical features." (PMID 31185985, 2019). "Several studies have indicated that MEK inhibitors can suppress the proliferation of colorectal cancer cells harboring KRAS or BRAF mutations in vitro and in vivo." (PMID 31769426, 2019). "We first examined the mutation status of the KRAS, PIK3CA and BRAF genes in human colorectal cancer cell lines." (PMID 31769426, 2019). "Sporadic MSI-H colorectal cancer is frequently associated with the v-raf murine sarcoma viral oncogene homolog B1 (BRAF) V600E mutation, through its association with the CpG island methylator phenotype." (PMID 31216061, 2019).
colorectal cancer (continued). "RAS and BRAF-mutated colorectal cancers are associated with resistance to chemotherapy and poor prognosis, highlighting the need for new therapeutic strategies." (PMID 31769426, 2019). "Right-sided colorectal cancers have had a significantly higher incidence of mutations in BRAF (8% vs 5%, p = 0.0001)." (PMID 31036005, 2019). "In this study, we estimated the performance of BNA-clamp PCR with Sanger sequencing method to detect KRAS, NRAS and BRAF mutations in colorectal cancers and compared the results from PCR-rSSO and NGS." (PMID 31711486, 2019). "In summary, this study demonstrated that overactivation of Akt is associated with MEK inhibitor resistance in colorectal cancer cells harboring KRAS or BRAF mutations and that Akt inhibitor overcame MEK inhibitor resistance." (PMID 31769426, 2019). "Mutations in either KRAS or BRAF drive colorectal cancers and predominate complementary pathways from EGFR that converge on FOXO3a." (PMID 30478887, 2019). "In cancer management, targeted therapy based on genetic data is widely applied (e.g., cetuximab for KRAS wild-type colorectal cancer, dabrafenib for cancers with V600E BRAF mutation)." (PMID 31167397, 2019). "With respect to tumor-associated glycosylation, we have determined that in colorectal cancer, BRAF mutations drive the expression of MGL ligands such as Tn antigen." (PMID 30761272, 2019). "The present study demonstrated that KRAS and BRAF mutations induce anoikis resistance in Caco-2 colorectal cancer cells." (PMID 31545494, 2019). "Our results demonstrated the BNA-clamp PCR method with Sanger sequencing have high accuracy for the detection of KRAS, NRAS and BRAF mutations in colorectal cancer." (PMID 31711486, 2019). "It is positive for urothelial carcinoma but can also mark the gastric and colorectal carcinomas, especially those with microsatellite status or with serrated pathway and BRAF mutations." (PMID 31205468, 2019). "Accordingly, in melanocytic cells BRAF mutation induces anoikis resistance by downregulating Bim, and in a colorectal carcinoma cell line with BRAF mutation (COLO205) repression of Bim inhibits apoptosis." (PMID 31545494, 2019). "More recent studies have confirmed the reduced overall survival in metastatic BRAF-mutated colorectal cancers (18.2 months), compared to that observed in metastatic BRAF-WT colorectal cancers (41.1 months)." (PMID 29652830, 2018). "The aim of FOCUS4-D was to test the efficacy of AZD8931 in patients with colorectal cancer whose tumours are wild-type for BRAF, PIK3CA, KRAS, and NRAS mutations." (PMID 29254887, 2018). "Gene mutations in high status MSI, BRAF, and N-ras differ according to gender among patients with colorectal cancer." (PMID 29976257, 2018). "Because sporadic MSI/dMMR phenotype in colorectal cancer is strongly associated with BRAF V600E mutation." (PMID 29659608, 2018). "Further studies are required to assess the utility of the BRAF V600E mutation as a biomarker for colorectal cancer and to fully exploit its predictive, prognostic, and therapeutic potential." (PMID 30598662, 2018). "Mutations of BRAF gene can also be found in colorectal cancer (CRC), papillary thyroid cancer, lung cancer and hairy cell leukemia." (PMID 29879227, 2018). "The BRAF V600E mutation occurs early in tumourigenesis and is highly correlated with the serrated neoplasia pathway of colorectal cancer." (PMID 30598662, 2018). "The remainder of this review will focus primarily on the more abundant BRAF V600E mutation and that which confers a significant clinical impact on colorectal cancer." (PMID 30598662, 2018). "The BRAF V600E mutation in colorectal cancer is an early event as indicated by its presence in one of the earliest forms of premalignant lesion, the hyperplastic or serrated aberrant crypt foci (ACF) (63%), but is rarely present in nonserrated ACF (6%)." (PMID 30598662, 2018).
colorectal cancer (continued). "KRAS and BRAF mutations are common in colorectal cancer and are associated with upregulation of GLUT1 and a glycolytic phenotype." (PMID 30018566, 2018). "This review highlights the importance of the BRAF mutation occurring in colorectal cancer stratified for molecular background and discusses its prognostic and clinical significance." (PMID 30598662, 2018). "In colorectal cancer, the BRAF V600E mutation accounts for the vast majority of all BRAF mutations and occurs in approximately 15%-20% of sporadic cases." (PMID 30598662, 2018). "The presence of the BRAF V600E mutation in colorectal cancer influences clinical presentation, histology, molecular parameters, and patient outcome." (PMID 30598662, 2018). "This platform identified KRAS and BRAF hot‐spot mutations following cfDNA isolation from the blood plasma and tissues obtained from 30 colorectal cancer patients." (PMID 30356899, 2018). "Colorectal cancers exhibiting a serrated phenotype, characterized by mutated BRAF, CIMP+ and MSS status are associated with a very poor prognosis." (PMID 29652830, 2018). "Sessile serrated adenoma/polyp is the main precursor lesion of the serrated pathway, in which the BRAF mutation can lead to colorectal cancer with the high MSI, CIMP-high or MSS, CIMP-high phenotype." (PMID 29652830, 2018). "Utilising this form of technology has highlighted the presence of non-V600 BRAF mutations that occur in cancers including colorectal cancer." (PMID 30598662, 2018). "Three patients were treated with imatinib, erlotinib, and vemurafenib on the basis of an Asp572Gly KIT mutation (lung cancer), an EGFR amplification (cervical cancer), and a Val600Glu BRAF mutation (colorectal cancer), respectively." (PMID 32914004, 2018). "An important subgroup of colorectal cancers bear a mutation in the BRAF oncogene and these cancers arise from serrated polyps initiated by the BRAF mutation." (PMID 29304767, 2018). "There is a very strong association between BRAF mutation in colorectal cancer and aberrant DNA methylation of CpG islands which is associated with gene silencing when it occurs in promoter areas." (PMID 29304767, 2018). "In contrast, BRAF mutant colorectal cancers with loss of MLH1 were more likely to harbor the A allele (P = 0.010)." (PMID 29304767, 2018). "In colorectal cancer, the presence of a BRAF mutation can be associated with an aggressive phenotype and is a key prognostic biomarker for poor outcome particularly in late-stage disease." (PMID 30598662, 2018). "Our data indicates a significant increase in the A-allele at MLH1–93 in BRAF mutant, mismatch repair deficient, dysplastic sessile serrated adenomas and colorectal cancers." (PMID 29304767, 2018). "Our study revealed that there is a gender-specific difference in patients with colorectal cancer regarding gene mutations of BRAF, N-ras, and high status MSI." (PMID 29976257, 2018). "There are some evidence that PIK3CA mutations associated with activation of KRAS- BRAF mutation occurring in colorectal cancers." (PMID 30774815, 2018). "Colorectal sessile serrated adenoma/polyps (SSA/Ps) are well-known precursors of colorectal cancer (CRC) characterized by BRAF mutation and microsatellite instability." (PMID 29435136, 2018). "Recent studies have explored the mechanism of resistance of BRAFV600E-mutated colorectal cancers to BRAF-inhibitors, showing that the mechanism of resistance implies alterations in elements of the RAS-RAF-MEK-ERK pathway." (PMID 29652830, 2018). "Sporadic MSI/MMR-deficient (dMMR) colorectal cancer is associated with the BRAF V600E mutation, though its association with CIMP (CpG island methylator phenotype) has been reported." (PMID 29976257, 2018). "BACKGROUND: CpG island methylator phenotype (CIMP) tumors, comprising 20% of colorectal cancers, are associated with female sex, age, right-sided location, and BRAF mutations." (PMID 30071442, 2018).
colorectal cancer (continued). "The efficiency of the combination of binimetinib and encorafenib plus cetuximab in the treatment of colorectal cancers harboring BRAF V600E mutations is in a phase III clinical development (NCT02928224)." (PMID 29455659, 2018). "About 20–30% of colorectal carcinomas develop via a serrated neoplasia pathway, thus defined according to the saw-toothed pattern of precursor polyp lesion; these tumors are usually BRAF or N-KRAS-mutated and are characterized by CIMP." (PMID 29652830, 2018). "Rare occurrences of BRAF mutations have been documented for conventional colorectal carcinomas, although they are frequent in dysplasia/carcinoma arising from SSA/Ps (50–90%)." (PMID 30458818, 2018). "The Ras pathway genes KRAS, BRAF, or ERBBs have somatic mutations in ~ 60% of human colorectal carcinomas." (PMID 29301589, 2018). "For example, in colorectal cancer, BRAF mutations are mutually exclusive with mutations in KRAS, indicating that a single alteration of the activity of a pathway member is sufficient to induce misregulation of that pathway." (PMID 28333948, 2017). "One example of the combined effect of genetics and epigenetics in the colorectal cancer development process is the presence of BRAF mutations as well as microsatellite instability in many CIMP tumours." (PMID 28106826, 2017). "In our study, CIMP-high was associated with BRAF mutation in both proximal colon and distal colorectal cancer." (PMID 28623901, 2017). "This is the first study that analyzed the association between altered miRNA expressions and BRAF mutations in colorectal cancer." (PMID 29115941, 2017). "In the current study, we assessed the mutation of RAS genes and BRAF gene, dMMR and their clinical correlations in 400 Chinese patients with stage I-IV colorectal cancers." (PMID 28416767, 2017). "In colorectal cancer, the BRAF V600E mutation results in DNA hypermethylation and CIMP development by upregulating the transcriptional repressor MAFG, which recruits the DNA methyltransferase DNMT3B to its targets at promoter CGIs." (PMID 29125844, 2017). "Yun and colleagues reported recently that the oxidised form of AA, dehydroascorbate (DHA) rather than AA was responsible for selectively killing glycolysis-driven colorectal cancer cells with BRAF and KRAS mutations." (PMID 28737676, 2017). "In this study, BRAF mutations were found in 4.0% of colorectal cancers, which is slightly lower than previous reports worldwide." (PMID 28583095, 2017). "We immunohistochemically evaluated EZH2 expression and assessed miR-31 and gene mutations [KRAS (codon 61/146), NRAS (codon 12/13/61), and BRAF (codon 600)] in 109 patients with colorectal cancer harboring KRAS (codon 12/13) wild-type." (PMID 28147317, 2017). "The BRAF-mutation-like subtype represents approximately 20% of colorectal cancers patients, of which ~10% are known BRAF mutated tumors and ~10% are BRAF wild-type tumors that share the same gene expression pattern." (PMID 29479053, 2017). "Nevertheless, it is noteworthy that SIRT1 was specifically over-expressed in colorectal serrated lesions with KRAS or BRAF mutations, possibly contributing to their malignant transformation into colorectal cancer." (PMID 28977971, 2017). "Both BRAF and KRAS oncogenes encode proteins involved in the MAPK pathway, and BRAF mutation has been reported to be mutually exclusive with KRAS mutation in colorectal cancer." (PMID 28623901, 2017). "Our study assessed the mutation of RAS genes and BRAF gene, dMMR and their clinical correlations in Chinese patients with colorectal cancers." (PMID 28416767, 2017). "In particular, right-sided tumors show a higher frequency of BRAF mutation and microsatellite instability and more often occur in patients with a genetic predisposition to colorectal cancer (e.g., Lynch syndrome)." (PMID 28598398, 2017).